TRIAP1 (TP53 regulated inhibitor of apoptosis 1)
Description:
Involved in the modulation of the mitochondrial apoptotic pathway by ensuring the accumulation of cardiolipin (CL) in mitochondrial membranes. In vitro, the TRIAP1:PRELID1 complex mediates the transfer of phosphatidic acid (PA) between liposomes and probably functions as a PA transporter across the mitochondrion intermembrane space to provide PA for CL synthesis in the inner membrane. Likewise, the TRIAP1:PRELID3A complex mediates the transfer of phosphatidic acid (PA) between liposomes (in vitro) and probably functions as a PA transporter across the mitochondrion intermembrane space (in vivo). Mediates cell survival by inhibiting activation of caspase-9 which prevents induction of apoptosis.
Synonyms: p53CSV; HSPC132; WF-1; MDM35
Tractability: Small molecule: a structure with a bound ligand is known. PROTAC: ubiquitination databases record sites on it.
Gene: Protein-coding gene on chromosome 12 (120,443,958 to 120,446,412, reverse strand). Ensembl gene ENSG00000170855.
Subcellular location: Mitochondrion; Mitochondrion intermembrane space
Subcellular location (Human Protein Atlas): Mitochondria; Nucleoplasm
Pathways (Reactome):
Metabolism of proteins: Mitochondrial protein degradation
Gene Ontology:
Molecular function: phosphatidic acid transfer activity; protein binding
Biological process: cellular response to UV; mitotic G1 DNA damage checkpoint signaling; negative regulation of apoptotic process; negative regulation of release of cytochrome c from mitochondria; phospholipid transport; positive regulation of phospholipid transport; positive regulation of transcription by RNA polymerase II; regulation of membrane lipid distribution
Cellular component: mitochondrial intermembrane space; mitochondrion; protein-containing complex
Genetic constraint (gnomAD): Loss-of-function variants: 7 observed, 7.36 expected, observed/expected ratio (o/e) 0.95, 90% interval 0.54 to 1.7. That is too few expected variants to judge how well the gene tolerates losing a copy. Missense variants: 84 observed, 97.81 expected, observed/expected ratio (o/e) 0.86, 90% interval 0.72 to 1.03. Synonymous variants: 35 observed, 36.24 expected, observed/expected ratio (o/e) 0.97, 90% interval 0.74 to 1.28.
Homologues: Orthologues: chimpanzee TRIAP1 (100% identical), macaque TRIAP1 (99% identical), mouse Triap1 (99% identical), rat Triap1 (99% identical), guinea pig TRIAP1 (97% identical), rabbit TRIAP1 (97% identical).
Diseases named in the same sentence as TRIAP1 in open-access papers:
TRIAP1 is named in the same sentence as 27 diseases in open-access papers, as found by Europe PMC text mining. Sharing a sentence is not in itself a finding about the gene and the disease. The quoted sentences say what the papers report.
nasopharyngeal carcinoma (6 papers, 2016 to 2023). A carcinoma arising from the nasopharyngeal epithelium. "Another study reported a new miR-320b/TRIAP1 pathway and that miR-320b acts as a posttranscriptional regulator of TRIAP1 expression in nasopharyngeal carcinoma." (PMID 33879126, 2021). "Studies have shown that TRIAP1 is involved in the occurrence of a variety of tumours, such as myeloma, ovarian cancer, and nasopharyngeal carcinoma." (PMID 33879126, 2021). "TRIAP1 is also found to be upregulated in multiple myeloma, and, in patients with nasopharyngeal carcinoma, TRIAP1 overexpression correlates with a poor survival rate." (PMID 30871022, 2019). "Previously, the relevance of TRIAP1 expression was also shown for the growth of nasopharyngeal carcinoma (NPC) tumors." (PMID 36387192, 2022).
osteosarcoma (6 papers, 2021 to 2024). A usually aggressive malignant bone-forming mesenchymal neoplasm, predominantly affecting adolescents and young adults. "Our findings first proved that the regulatory role of circPVT1 in DXR resistance of osteosarcoma was mediated by the miR-137/TRIAP1 axis, providing an underlying circRNA-targeted therapy for osteosarcoma." (PMID 33981772, 2021). "A prior study has pointed out that TRIAP1 was implicated in chemosensitivity in osteosarcoma." (PMID 33981772, 2021). "TRIAP1 is participated with the process of many cancers, including osteosarcoma (OS), gastric cancer, and ovarian cancer." (PMID 39135128, 2024). "For example miRNA-539 can inhibit the proliferation, migration and invasion of osteosarcoma cells by targeting TRIAP1, and promote the apoptosis of osteosarcoma cells." (PMID 35480301, 2022). "For example, miRNA-30a-3p was found to inhibit GC cell proliferation and migration by targeting APBB2; miRNA-539 inhibited osteosarcoma cell proliferation, apoptosis, invasion and migration by targeting TRIAP1." (PMID 36203485, 2022). "In the manuscript, an apparent increase of TRIAP1 was viewed in DXR-resistant osteosarcoma tissues and cell lines." (PMID 33981772, 2021). "In osteosarcoma cells, TRIAP1 was increased and participated in the epirubicin-mediated antiproliferation and proapoptosis." (PMID 33981772, 2021). "A previous study has reported that the decrease in TRIAP1 expression is related to the enhancement of chemosensitivity in osteosarcoma." (PMID 33879126, 2021). "In this study, we found that the inhibitory role of miR-539 in the initiation and progression of osteosarcoma was achieved by targeting TRIAP1." (PMID 33879126, 2021). "All these results indicate that miRNA-539 can inhibit the growth of osteosarcoma by decreasing the expression of TRIAP1." (PMID 33879126, 2021). "TRIAP1 was found to be the potential target gene of miRNA-539 by online bioinformatics software and the expression level of TRIAP1 in osteosarcoma cells overexpressing miRNA-539 was detected by qT-PCR." (PMID 33879126, 2021). "circPVT1 boosted DXR resistance of osteosarcoma cells partly by regulating the miR-137/TRIAP1 axis, hinting a promising therapeutic target for the osteosarcoma treatment." (PMID 33981772, 2021). "Meanwhile, we further proved that both mRNA level and protein level of TRIAP1 were distinctly upregulated in the DXR-resistant osteosarcoma cells (KHOS/DXR and U2OS/DXR) in comparison with other cells." (PMID 33981772, 2021). "Next, we explored the regulatory role of miR-137 and TRIAP1 on DXR resistance in osteosarcoma cells." (PMID 33981772, 2021). "It has been reported that TRIAP1 was related to drug chemosensitivity in osteosarcoma cells." (PMID 33981772, 2021). "So, the expression level of TRIAP1 was examined in osteosarcoma." (PMID 33981772, 2021). "In addition, we found that TRIAP1 was the target of miRNA-539, as the expression level of TRIAP1 in osteosarcoma cells transfected with miRNA-539 mimics significantly decreased." (PMID 33879126, 2021). "In this study, we found that miR-539 inhibited cell proliferation, invasion and migration of osteosarcoma in vitro and in vivo, which may occur mechanistically through targeting TRIAP1." (PMID 33879126, 2021). "MiRNA-539 may inhibit the cell proliferation, migration and invasion of osteosarcoma cells and promote the apoptosis of osteosarcoma cells by targeting on TRIAP1." (PMID 33879126, 2021). "Also, the TRIAP1 level was inversely related to miR-137 in osteosarcoma tissues." (PMID 33981772, 2021). "Thus, the purpose of this study was to prove the role of circPVT1 and to explore whether the involvement of circPVT1 on DXR resistance in osteosarcoma was regulated by the miR-137/TRIAP1 axis." (PMID 33981772, 2021).
osteosarcoma (continued). "In addition, mechanistic analysis verified that miR-137 inhibitor could partly overturn the suppression effect of circPVT1 silencing on the TRIAP1 level in DXR-resistant osteosarcoma cells, validating that circPVT1 could function as a sponge of miR-137 to upregulate TRIAP1 expression." (PMID 33981772, 2021). "circPVT1 and TRIAP1 were highly expressed, and miR-137 was decreased in DXR-resistant osteosarcoma tissues and cells." (PMID 33981772, 2021). "However, the role of TRIAP1 in DXR resistance in osteosarcoma is still largely unknown." (PMID 33981772, 2021). "Interestingly, there was a negative correlation between TRIAP1 and miR-137 in osteosarcoma tissues." (PMID 33981772, 2021).
breast cancer (4 papers, 2019 to 2024). A primary or metastatic malignant neoplasm involving the breast. "TRIAP1 is also involved in prostate cancer bone metastasis and sensitivity to doxorubicin in breast cancer cells." (PMID 30871022, 2019).
gastric cancer (4 papers, 2008 to 2024). A primary or metastatic malignant neoplasm involving the stomach. "In conclusion, the results of this study show that miR-107 can inhibit the proliferation of gastric cancer in vivo and in vitro by targeting TRIAP1." (PMID 35480301, 2022). "However, the regulatory role of miR-107 and TRIAP1 and the biological role of TRIAP1 in gastric cancer are not yet known." (PMID 35480301, 2022).
ovarian carcinoma (4 papers, 2019 to 2024). A malignant neoplasm originating from the surface ovarian epithelium. "For instance, a previous study revealed that TRIAP1 was the direct target gene of miR-18a in ovarian cancer." (PMID 33879126, 2021). "In ovarian cancer cells, increased TRIAP1 levels correlate with increased proliferation, a decrease in apoptosis and overall tumour progression." (PMID 30871022, 2019).
prostate carcinoma (4 papers, 2014 to 2023). A carcinoma that arises from epithelial cells of the prostate gland. "(A) Prostate cancer cells were transiently transfected with an expression vector encoding for human TRIAP1-GFP." (PMID 30871022, 2019). "(C) Cell cycle analysis of TRIAP1-GFP transfected prostate cancer cell lines was performed using Nicoletti/PI staining and flow cytometry." (PMID 30871022, 2019). "Interestingly, immunohistological analysis of TRIAP1 in advanced human prostate cancer reveals increased TRIAP1 immunoreactivity in the malignant epithelial cells of the more radioresistant higher Gleason grade adenocarcinomas." (PMID 30871022, 2019). "Paraffin-sections of human prostate cancers were stained for TRIAP1." (PMID 30871022, 2019). "To further investigate a potential TRIAP1-mediated radiation resistance of prostate carcinoma cells caused by the stromal compartment, we generated TRIAP1-overexpressing WPMY-1 fibroblasts via transfection of WPMY-1 with an expression vector encoding for human TRIAP1 tagged with GFP." (PMID 30871022, 2019). "Thus, increased expression and secretion of TRIAP1 by CAV1-silenced fibroblasts suggests that secreted TRIAP1 and then internalized by neighbouring prostate cancer cells, might account for the induced radiation resistance of these cells." (PMID 30871022, 2019). "Further research showed that cotransfection of a miR-506-3p inhibitor with a TRIAP1 overexpression plasmid restored the suppressive effect of PCGEM1 knockdown on the proliferation, migration and invasion of prostate cancer." (PMID 35109849, 2022). "We then investigated if the induced resistance of prostate cancer cells, after treatment with supernatants derived from CAV1-proficient or -deficient fibroblasts, led to higher TRIAP1 levels (not shown)." (PMID 30871022, 2019). "The cell cycle of DU145 prostate carcinoma cells after TRIAP1 transfection was not affected upon radiation." (PMID 30871022, 2019).
lung cancer (3 papers, 2022 to 2024). A malignant neoplasm involving the lung. "For example, miR-107 regulates the proliferation and apoptosis of lung cancer cells by targeting TRIAP1." (PMID 35480301, 2022). "Knockdown of TRIAP1 inhibited the ability of proliferation, apoptosis, migration and invasion of thyroid cancer, oral squamous cell carcinoma (OSCC) and Lung cancer cells." (PMID 35109849, 2022).
multiple myeloma (3 papers, 2019 to 2022). "Disruption of the TRIAP1-PRELI complex reduces levels of PA transfer from the ER into the mitochondrial inner membrane and CL production, which facilitates the release of CYTC and apoptosis, a mechanism that possibly explains why TRIAP1 is upregulated in multiple myeloma." (PMID 36158205, 2022). "Moreover, a six-gene risk score model (ZNF486, EPHA5, RP11.326C3.15, DUSP6, DUSP10, and TRIAP1) for the prognostic prediction of PI-treated myeloma patients was developed by the random survival forest variable hunting (RSF-VH) algorithm." (PMID 33344452, 2020).
colon cancer (2 papers, 2016 to 2022). "In this study, we found that knockdown of TRIAP1 induced mitochondrial fragmentation, membrane potential depolarization and the subsequent release of cytochrome c, and enhanced apoptosis in NPC cells, which is consistent with a previous study in colon cancer." (PMID 27428374, 2016).
colorectal cancer (2 papers, 2022 to 2024). A primary or metastatic malignant neoplasm that affects the colon or rectum. "In our research, the treatment of colorectal cancer cells with OMe-Ph-Elemene led to the modulation of several crucial proteins associated with oxidative stress and cell apoptosis, including TRIAP1, HMOX1, and CISD3." (PMID 39765827, 2024). "Here, we report that in a cellular model of colorectal cancer, TRIAP1 expression supports cancer cell proliferation and tumorigenesis." (PMID 36387192, 2022). "Here, in a colorectal cancer cell model, we report that the expression of TRIAP1 supports cancer cell proliferation and tumorigenesis." (PMID 36387192, 2022). "Overall, the comprehensive combination of lipidomic and metabolomic data indicates that TRIAP1 deficiency results in changes in global lipidic and metabolic profiles of HCT116 colorectal cancer cells." (PMID 36387192, 2022). "In this study, OMe-Ph-Elemene reduced TRIAP1 in CRC cells, leading to inhibition of colorectal cancer cell proliferation and promotion of apoptosis." (PMID 39765827, 2024). "As TRIAP1 was found overexpressed in various cancer cells, we explored the potential impact of its overexpression in HCT116 cells derived from a colorectal cancer." (PMID 36387192, 2022). "Taken together, our observations show that the depletion of TRIAP1 in human colorectal cancer cells affects mitochondrial morphology without having a significant impact on the biogenesis or activity of individual RC complexes." (PMID 36387192, 2022).
thyroid cancer (2 papers, 2022). "The lncRNA MFI2-AS1/miR-125a-5p axis up-regulates TRIAP1 to promote thyroid cancer tumorigenesis, and the regulatory effects of miR-107 and TRIAP1 have also been studied." (PMID 35480301, 2022).
non-small cell lung carcinoma (1 paper, 2022). A group of at least three distinct histological types of lung cancer, including non-small cell squamous cell carcinoma, adenocarcinoma, and large cell carcinoma. "TRIAP1 also increased the risk of recurrence or metastasis in afflicted patients with non-small cell lung cancer (NSCLC) following irradiation." (PMID 35109849, 2022).
penile carcinoma (1 paper, 2022). "TRIAP1 was significantly in penile carcinoma (PeCa), TRIAP1 expression was significantly related with the histological grade and the local recurrence rate." (PMID 35109849, 2022).
prostate tumours (1 paper, 2019). "Thus, in line with the in vitro results, TRIAP1 derived from stromal fibroblasts is able to induce radiation resistance of prostate tumours." (PMID 30871022, 2019).
thyroid (1 paper, 2022). "For instance, lncRNA MFI2-AS1 is overexpressed during thyroid tumorigenesis and contributes to thyroid carcinogenesis partially by pairing to miR-125a-5p to induce TRIAP1." (PMID 35443670, 2022).